ADAM17 (ADAM metallopeptidase domain 17)
Diseases named in the same sentence as ADAM17 in open-access papers (continued):
Sharing a sentence is not in itself a finding about the gene and the disease.
viral infection (32 papers, 2013 to 2024). "Interestingly, the ACE2 cytoplasmic tail, as well as ADAM17 expression have been found to be necessary to viral infection; however, the underlying mechanism by which ACE2 tail-mediated ADAM17 activation facilitates viral entry is still unclear." (PMID 33357215, 2020). "Under viral infection contexts (influenza virus and human papilloma virus), ADAM17 attacks the cellular machinery and deregulates the notch pathway to improve the infection." (PMID 34445140, 2021). "Nevertheless, ADAM17/TACE-mediated ACE2 shedding or ACE2 enzymatic activity have been shown to intriguingly correlate positively with viral infection and disease complications." (PMID 32708755, 2020). "Interestingly, broad specificity inhibitors, such as BB-94, and prinomastat, consistently suppressed the viral infection better than ADAM17 or ADAM 10 specific inhibitors." (PMID 38572241, 2024). "Finally, beyond the proinflammatory signalling and virus infections, dysregulated ADAM17 is involved in cancer progression through proteolytic release of EGF receptor ligands." (PMID 37119365, 2023). "The mechanism of action of ADAM17 in viral infection requires more research evidence." (PMID 36366532, 2022). "Lung tissue cell analysis showed that ADAM17 protein was highly expressed in respiratory epithelial cells of the nasopharynx and bronchus, suggesting that viral infection may be mainly distributed in respiratory epithelial cells." (PMID 35720350, 2022). "Thus, ADAM17 should be considered a potential target for drug discovery that regulates host reactivity to viral infection and prevents fatal outcomes." (PMID 35720350, 2022). "Future studies evaluating the role of ADAM17 in other forms of liver disease including viral infection, autoimmune hepatitis, and drug induced liver injury may shed more light into this context dependent role of ADAM17 in liver health." (PMID 35095853, 2021). "Neopterin may therefore serve both as a biomarker of an early inflammatory state based on IFN-γ signaling, which should be associated with a large quantity of surface bound TNF-α ready for secretion upon an acute event, such as viral infection and ADAM17 induction." (PMID 34497777, 2021). "Similarly, ADAM17 silencing in primary porcine fibroblasts significantly impaired virus infection." (PMID 33684175, 2021). "Additionally, we hypothesize that an early peak in ANG II and ADAM-17 might represent a physiological attempt to reduce viral infection via tACE2." (PMID 33519802, 2020). "Our study illustrated that, analogous to other viral infections, HIV-1/SIV infection also reduced CD16 expression via ADAM17 elevation, and this interaction can be therapeutically targeted to restore NK cell functions." (PMID 37669308, 2023). "Furthermore, strategies targeting iRhom functions to modulate ADAM17 activity and cell surface localisation may have beneficial implications for the prevention and treatment of viral diseases in humans and cattle due to the role of ADAM17 in SARS-CoV1/2 and pestivirus infections, respectively." (PMID 37119365, 2023). "Along with the link between surface receptor expression and downstream intracellular signaling, this study explicated the reduction of CD16 via an IL-18/ADAM17-driven mechanism in HIV-1/SIV infection, as seen in other viral infections." (PMID 37669308, 2023). "It remains possible that these sheddases are activated during the early phase of infection to induce the release of sE-Cad and sACE2 following viral infection and then that a feedback regulation loop down-modulates the ADAM-10 and ADAM-17 genes expression." (PMID 35601094, 2022). "As ADAM17 is a type I multi-domain transmembrane protein, and participates in the hydrolysis and shedding of ACE2, the latter of which further aggravates viral infection." (PMID 35720350, 2022).
viral infection (continued). "One final possible consequence of viral infection is the internalization of ACE2 receptor from the surface of epithelial cells in the pulmonary alveoli, AT1Rs activation, and ADAM-17 and TMPRSS2 cleavage." (PMID 33357215, 2020). "Compared with virus infection alone, PAMs co-treated with LPS and PRRSV showed higher transcription level of ADAM17 at every time point of infection." (PMID 32269560, 2020). "Suppression of ADAM17 by reducing the shedding of ACE2 may reduce viral load and protect host cells from viral infection." (PMID 36558177, 2022). "ADAM17, as a type I multi-domain transmembrane protein, has a similar function to ACE2 and contributes to the hydrolysis and shedding of ACE2, while an increase in shedding of ACE2 can aggravate viral infection." (PMID 35720350, 2022). "This indicates that ADAM17−/− CD8+ T cells can traffic to the lung, where they appropriately recognize viral antigen, and express effector activities required for protection from lethal viral infection." (PMID 24223177, 2013). "Although the reduction of sACE2 was clearly less than the degree of inhibition of viral infection, we considered the possibility that ADAM17‐mediated shedding of ACE2 and the resulting release of sACE2 may be an additional mechanism through which ADAM17 contributes to SARS‐CoV‐2 infection." (PMID 35527514, 2022). "Interestingly, we observed in mouse PCLS no induction of Il6r or Il6st gene expression upon virus infection, but BRO upregulated both Il6r and Il6st, as well as Adam17 in the presence but also in the absence of virus." (PMID 31067687, 2019). "Thus, ADAM17 is required for proteolytic processing and release of sTNF-α by CD8+ T cells, but it is not required for other CD8+ T-cell effector functions in virus infection." (PMID 24223177, 2013).
Sepsis (31 papers, 2013 to 2025). Sepsis is defined as life-threatening organ dysfunction caused by a dysregulated host response to infection. "SNPs of ADAM17 have been implicated in several disorders, including Parkinson’s disease, allergy, sepsis, and vascular diseases." (PMID 38881671, 2024). "Supporting an important role for the regulation of cell activation by ADAM17, ADAM17 deficiency in humans has been associated with severe inflammatory disorders of the skin and the gut, resulting in recurrent sepsis and poor survival." (PMID 31507592, 2019). "A recent study has also provided evidence that ADAM17 promoter polymorphism rs12692386 is a functional variant associated with the progression of sepsis severity." (PMID 28487846, 2017). "They found that the chimeric mouse harboring ADAM17-deficient leukocytes had longer survival after Escherichia coli-mediated peritoneal sepsis, which was associated with a reduction in systemic proinflammatory cytokine levels, including TNF, and bacterial burden." (PMID 33579029, 2021). "Moreover, in patients, ADAM17 activity and a functional polymorphism of its gene corresponded with sepsis progression." (PMID 32932701, 2020). "Deficiency of ADAM17 in leukocytes resulted in enhanced recruitment of neutrophils to the site of infection, decreased bacterial load, and improved survival in both polymicrobial sepsis and peritonitis." (PMID 33392273, 2020). "Studies in sepsis animal models have shown that reducing ADAM17 expression decreases serum levels of IL-1β, IL-6, and TNF-α while also decreasing ICAM-1 and VCAM-1 expression in lung and liver tissues, thereby significantly improving 72-h survival in mice." (PMID 41280722, 2025). "This work demonstrated significant sepsis survival following delivery of ADAM17 mAb MEDI3622 both prior to and following infection induction, establishing ADAM17 as the prospective therapeutic target for sepsis control." (PMID 36979744, 2023). "Taking this into account, a recombinant prodomain peptide of ADAM17 was synthesized and shown to be an effective and highly specific inhibitor of ADAM17 activity in sepsis and inflammation models and a murine kidney fibrosis model." (PMID 35158891, 2022). "As there is no specific marker of cardiac fibroblast, we created a mouse model of fibroblast-specific knockout of ADAM17 and found severe sepsis and high mortality in these mice with unclear mechanism." (PMID 36313337, 2022). "When the ADAM17 mAb was combined with antibiotic administration, sepsis survival was markedly enhanced compared to either intervention alone, which was associated with a significant reduction in plasma levels of various inflammation-related factors." (PMID 32932701, 2020). "For this study, we evaluated for the first time the effects of an ADAM17 function blocking monoclonal antibody (mAb) on the pathogenesis of polymicrobial sepsis." (PMID 32932701, 2020). "In the current study, we investigated for the first time the in vivo effects of systemic ADAM17 inhibition using a function blocking monoclonal antibody (mAb) on sepsis resistance." (PMID 32932701, 2020). "Mice treated with the ADAM17 mAb MEDI3622 prior to sepsis induction exhibited significantly decreased mortality." (PMID 32932701, 2020). "In a model of polymicrobial sepsis, these conditional ADAM17 knockout mice also demonstrated enhanced survival, which corresponded with decreased bacteremia and levels of circulating proinflammatory cytokines, key determinants of sepsis severity." (PMID 28487846, 2017). "This review provides an overview of ADAM17 function and regulation and its potential contribution to neutrophil dysfunction during sepsis." (PMID 28487846, 2017). "Several lines of evidence from animal models and patients indicate aberrant ADAM17 activity during sepsis." (PMID 28487846, 2017). "Of course, extrapolation of mouse model findings related to the effects of ADAM17 inactivation need to be confirmed in humans in which sepsis is a highly complex clinical syndrome." (PMID 28487846, 2017).
Sepsis (continued). "The potential benefits of ADAM17 inhibition on increasing neutrophil infiltration at sites of infection and reducing damaging inflammation may be exploited in clinical settings to reduce sepsis progression as well as its occurrence in high risk, general surgery patients." (PMID 28487846, 2017). "ADAM17 upregulation might be beneficial in sepsis, and our RNA-seq analysis showed that ADAM17 was extensively dispersed among various immune cell kinds." (PMID 40258762, 2025). "Importantly, two studies showed that the rs12692386 A > G allele of ADAM17 increased the protease expression and shedding of TNF, IL-6R, and CX3CL1, conferring a higher risk of severe disease and shock in sepsis." (PMID 38881671, 2024). "Indeed, it was found that in murine polymicrobial sepsis, ADAM17 controls neutrophil recruitment and that ADAM17 levels and/or activity are elevated in sepsis models and in renal disease." (PMID 35681510, 2022). "Recently, we identified compound heterogeneous missense ADAM17 variants through targeted panel sequencing (TPS) in the Japanese male infant with erythroderma and exudate in whole body, recurrent skin infection, pneumonia and sepsis and prolonged diarrhoea." (PMID 33953303, 2021). "Our results indicate that the combination of blocking ADAM17 as an immune modulator and appropriate antibiotics may provide a new therapeutic avenue for sepsis treatment." (PMID 32932701, 2020). "For instance, mice with ADAM17-null leukocytes showed significantly improved survival during monomicrobial and polymicrobial sepsis, and this increased resistance corresponded with higher neutrophil recruitment at sites of infection and decreased bacterial levels locally and systemically." (PMID 32932701, 2020). "We have reported that during sepsis, ADAM17 promotes neutrophil paralysis." (PMID 32932701, 2020). "We have reported that conditional knockout mice lacking ADAM17 in all leukocytes had a survival advantage during sepsis, which was associated with improved neutrophil effector functions." (PMID 32932701, 2020). "These and other findings indicate aberrant ADAM17 activity during sepsis." (PMID 32932701, 2020). "Thinking about treatment options, e.g., for polymicrobial sepsis, ADAM17 might be a suitable target in infectious diseases." (PMID 33392273, 2020). "Indeed, ADAM17 upregulation on the surface of circulating neutrophils was found to correlate with sepsis severity and patient outcome." (PMID 28487846, 2017). "This involves ADAM17 as indicated by increased levels of its cleaved substrates in the blood of septic patients, and that ADAM17 inactivation improves neutrophil recruitment and bacterial clearance in animal models of sepsis." (PMID 28487846, 2017). "Sepsis may result in an over-induction of ADAM17 activity in neutrophils, endothelial cells, and other cells that in turn undermines the necessary balance between intravascular adhesion and de-adhesion events, and impairs neutrophil recruitment at the locus of infection." (PMID 28487846, 2017). "Moreover, the ADAM17 substrate TNFα occurs at high levels in the blood during sepsis promoting neutrophil rigidity and the upregulation of integrin adhesion molecules, in turn causing occlusion of the microvasculature, ischemia, and tissue destruction through the release of cytotoxic factors." (PMID 28487846, 2017). "In sepsis, the TNF-α/NF-κB pathway—an essential signaling axis that drives endothelial inflammation—is activated by ADAM17, thereby inducing endothelial inflammation, apoptosis, and barrier dysfunction." (PMID 41280722, 2025). "These targets, including ADAM17, CD81, CASP1, and MGMT, lay the foundation for further research into the mechanisms of action of Calculus Bovis in sepsis treatment." (PMID 40258762, 2025). "Although ADAM10 and ADAM17 have been extensively studied in contexts such as atherosclerosis, the role of ADAM8 in sepsis-induced cardiac dysfunction remains poorly understood." (PMID 41169382, 2025).
Sepsis (continued). "ADAM17 cleaves TNF and IL-6 receptor and is a central drug target for inflammatory conditions, such as sepsis and rheumatoid arthritis." (PMID 40081988, 2025). "Indeed, a stable form of the ADAM17 prodomain attenuated ADAM17-mediated disease models of sepsis, rheumatoid arthritis and inflammatory bowel disease via inhibiting TNFα secretion, thus providing in vivo evidence as a potential new highly selective inhibitor of ADAM17." (PMID 31438559, 2019). "Sepsis induced the expression of three members of the disintegrin and metalloproteinase (ADAM) family, ADAM17, ADAM19 and ADAM10, and compstatin treatment mitigated the enhancement of these genes." (PMID 26337158, 2015). "The analysis of immunofluorescence images and tissue-specific expression data revealed the different expression patterns of ADAM17, MGMT, CD81, and CASP1 at the cellular level and tissue level, which lays the foundation for further investigation of their roles in sepsis." (PMID 40258762, 2025). "Genetic attenuation of ADAM17 in myeloid cells or hepatocytes reduces circulating TNF-α levels and improves survival following LPS challenge, while small-molecule ADAM17 inhibitors have demonstrated anti-inflammatory effects in sepsis models." (PMID 41465816, 2025). "Hence, ADAM17, CASP1, CD81, and MGMT are likely to be potential core targets in Calculus Bovis treatment for sepsis." (PMID 40258762, 2025). "In agreement, iRhom2-deficient mice show no evident abnormalities, but they are protected against sepsis, RA, lupus nephritis and hemophilic arthropathy, majorly due to blocking the iRhom2/ADAM17/TNF pathway." (PMID 33579029, 2021). "The use of active-site ADAM10 inhibitors such as GI254023X has shown promising preclinical results to improve sepsis; however, the evaluation of these agents in humans remains limited by nonspecific inhibitory effects on ADAM17 and unfavorable toxicities with chronic use." (PMID 37788087, 2023). "Thus, temporarily targeting ADAM17 for sepsis with highly specific inhibitors may not result in significant adverse effects." (PMID 28487846, 2017).
colon carcinoma (29 papers, 2010 to 2025). "In this study, we analyzed naturally occurring mutations within the ADAM17 gene found in colon cancer tissues, utilizing databases (IntOGen, COSMIC, TCGA and ICGC) containing sequence data of patient tumor samples." (PMID 33143292, 2020). "In this study, we focused on missense point mutations identified in colon cancer samples (in total 11 different ADAM17 variants were found)." (PMID 33143292, 2020). "We here selected three ADAM17 missense point mutations from colon cancer tissue (E319G, E406X, M435I) as well as one variant found within pancreatic cancer (P417Q)." (PMID 33143292, 2020). "Altogether, the colon cancer-associated ADAM17 mutations analyzed in this study either negatively affected shedding ability and/or intracellular trafficking." (PMID 33143292, 2020). "In mice, ADAM17-deficiency has a protective effect on tumor burden in an induced genetic colon cancer model." (PMID 33143292, 2020). "Overall, our data indicate that colon cancer-associated ADAM17 variants (E319G, E406X, M435I) exhibit diminished substrate recognition and/or enzymatic activity towards physiological substrates of the metalloprotease (TNFα, IL-6R, AREG)." (PMID 33143292, 2020). "The role of ADAM17 in colon cancer is thought to be linked to ADAM17-mediated shedding of EGF-R activating ligands, as well as IL-6 trans-signaling, which is also promoted by ADAM17 via the shedding of IL-6R." (PMID 33143292, 2020). "Upregulation of both pathways are hallmarks and high risk factors of colon cancer and their activation is mediated and regulated by ADAM17, underlining its role in pathology." (PMID 33143292, 2020). "Since recent mouse data pointed to an important role of ADAM17 in colon cancer development, we focused on ADAM17 mutations found within the large intestine." (PMID 31060243, 2019). "Underlining the link between colon cancer and ADAM17, genetic intestinal cancer models in ADAM17-deficient mice show a reduced tumor burden." (PMID 31060243, 2019). "In this study, we characterized naturally occurring point mutations found in colon cancer tissue of patients within the pro-, membrane-proximal- and cytoplasmic-domain to unravel regulatory mechanisms of ADAM17 maturation, trafficking and proteolytic activity." (PMID 31060243, 2019). "Databases (IntOGen, COSMIC, TCGA and ICGC) listing somatic mutations in cancer tissue were searched for mutations within the ADAM17 gene in colon cancer samples." (PMID 31060243, 2019). "In this study, we characterize point mutations within the ADAM17 gene found in the tissue of colon cancer patients." (PMID 31060243, 2019). "In the present study, we screened databases containing somatic ADAM17 mutations in tumor samples from colon cancer patients revealing coding mutations within all domains of ADAM17." (PMID 31060243, 2019). "Our data provide evidence that overall colon cancer-associated ADAM17 variants in the MPD and CD lack sufficient cell surface trafficking, but vary only slightly in their proteolytic activity in comparison to the wildtype (wt) construct." (PMID 31060243, 2019). "Taken together, our data indicate that colon cancer-associated ADAM17 mutations negatively affect protein maturation and transport via the secretory pathway." (PMID 31060243, 2019). "In this study, we chose four ADAM17 variants located within the catalytic domain for analysis: three were found in colon cancer samples (E319G, E406X, M435I) and one in pancreatic cancer (P417Q), all of them resulting in an amino acid change or the introduction of an early stop codon." (PMID 33143292, 2020). "At least for the here analyzed ADAM17 variants, their involvement in colon cancer might have different underlying causes." (PMID 31060243, 2019).